PLEKHM2 (pleckstrin homology and RUN domain containing M2)
Description:
Plays a role in lysosomes movement and localization at the cell periphery acting as an effector of ARL8B. Required for ARL8B to exert its effects on lysosome location, recruits kinesin-1 to lysosomes and hence direct their movement toward microtubule plus ends. Binding to ARL8B provides a link from lysosomal membranes to plus-end-directed motility. Critical factor involved in NK cell-mediated cytotoxicity. Drives the polarization of cytolytic granules and microtubule-organizing centers (MTOCs) toward the immune synapse between effector NK lymphocytes and target cells. Required for maintenance of the Golgi apparatus organization. May play a role in membrane tubulation.
Synonyms: KIAA0842; SKIP
Tractability: Small molecule: a structure with a bound ligand is known. Antibody: UniProt places it where antibodies can reach, with high confidence. PROTAC: ubiquitination databases record sites on it; its protein half-life has been measured.
Gene: Protein-coding gene on chromosome 1 (15,681,461 to 15,734,769, forward strand). Ensembl gene ENSG00000116786.
Subcellular location: Cytoplasm; Lysosome membrane
Gene Ontology:
Molecular function: kinesin binding; protein binding
Biological process: Golgi organization; lysosome localization; natural killer cell mediated cytotoxicity; regulation of protein localization
Cellular component: cytoplasm; endosome membrane; lysosomal membrane
Genetic constraint (gnomAD): Loss-of-function variants: 73 observed, 81.67 expected, observed/expected ratio (o/e) 0.89, 90% interval 0.74 to 1.09. The upper end of that interval is the gene's LOEUF score, 1.09, which puts it in group 4 of 6, group 1 being the genes least tolerant of losing a copy. Missense variants: 1,124 observed, 1,169.9 expected, observed/expected ratio (o/e) 0.96, 90% interval 0.91 to 1.01. Synonymous variants: 545 observed, 491.56 expected, observed/expected ratio (o/e) 1.11, 90% interval 1.03 to 1.19.
Gene-disease validity (ClinGen):
ClinGen rates the evidence that PLEKHM2 causes each of these diseases.
dilated cardiomyopathy (autosomal recessive): Moderate. Cardiomyopathy which is characterized by dilation and contractile dysfunction of the left and right ventricles.
Homologues: Orthologues: chimpanzee PLEKHM2 (99% identical), macaque PLEKHM2 (99% identical), dog PLEKHM2 (91% identical), pig PLEKHM2 (90% identical), mouse Plekhm2 (89% identical), rat Plekhm2 (89% identical), guinea pig PLEKHM2 (87% identical), rabbit PLEKHM2 (86% identical), zebrafish plekhm2 (59% identical), tropical clawed frog plekhm2 (57% identical), Drosophila melanogaster CG31064 (9% identical), Drosophila melanogaster CG6051 (8% identical), and 1 more. Paralogues in human: ZFYVE26 (12% identical), RUFY1 (12% identical), SNX29 (12% identical), RUFY2 (11% identical), RUFY3 (10% identical), ZFYVE28 (9% identical), RUNDC3B (8% identical), ZFYVE1 (8% identical), RUNDC3A (7% identical), ZFYVE16 (7% identical), ZFYVE19 (7% identical), PLEKHF1 (5% identical), and 1 more.
Diseases named in the same sentence as PLEKHM2 in open-access papers:
PLEKHM2 is named in the same sentence as 21 diseases in open-access papers, as found by Europe PMC text mining. Sharing a sentence is not in itself a finding about the gene and the disease. The quoted sentences say what the papers report.
dilated cardiomyopathy (6 papers, 2022 to 2025). "Pleckstrin homology domain-containing family M member 2 (PLEKHM2) is an essential adaptor for lysosomal trafficking and its homozygous truncation have been reported to cause early onset dilated cardiomyopathy (DCM)." (PMID 38490981, 2024). "A two-base deletion mutation in PLEKHM2 was identified in patients suffering from dilated cardiomyopathy (DCM) and left ventricular noncompaction (LVNC)." (PMID 41134891, 2025). "We recently linked a recessive inherited mutation in PLEKHM2 to a familial form of dilated cardiomyopathy and left ventricular non-compaction." (PMID 38942823, 2024). "Pleckstrin Homology And RUN Domain Containing M2 (PLEKHM2) [delAG] mutation causes dilated cardiomyopathy with left ventricular non-compaction (DCM-LVNC), resulting in a premature death of PLEKHM2[delAG] individuals due to heart failure." (PMID 36555735, 2022). "Recently, a novel mutation in the Pleckstrin Homology And RUN Domain Containing M2 (PLEKHM2) gene, PLEKHM2[delAG], was linked to a rare and fatal cardiovascular disease called dilated cardiomyopathy with left ventricular non-compaction (DCM-LVNC)." (PMID 36555735, 2022).
cardiomyopathy (5 papers, 2020 to 2025). A disease of the heart muscle or myocardium proper. "Another study by Akins et al2 described a 21-year-old woman with DCM carrying 2 heterozygous variants in PLEKHM2, including a frameshift mutation and a splice variant, further supporting the gene’s role in cardiomyopathy." (PMID 40054934, 2025). "And PLEKHM2-WT overexpression restored autophagic flux and ameliorated mitochondrial function, ultimately rescued PLEKHM2-deficient cardiomyopathy." (PMID 38490981, 2024). "The observed dysregulation in these genes highlight a disruption of mitochondrial homeostasis in PLEKHM2-deficient cardiomyopathy." (PMID 38490981, 2024). "To assess for potentially pathogenic effects of PLEKHM2-deficient cardiomyopathy, we performed quantitative transcriptome profiling by RNA-seq." (PMID 38490981, 2024). "In PLEKHM2-deficient cardiomyopathy, ROS also played a critical role in mediating extensive Δψm destabilization and abnormal calcium handling." (PMID 38490981, 2024). "Here, we generated an in vitro model of PLEKHM2 knockout (KO) induced pluripotent stem cell-derived cardiomyocytes (hiPSC-CMs) to elucidate the potential pathogenic mechanism of PLEKHM2-deficient cardiomyopathy." (PMID 38490981, 2024). "This newly identified feature of the mutated PLEKHM2-dependent cardiomyopathy indicates that the function of PLEKHM2 protein is crucial to maintain myocardial tissue viability over time." (PMID 37349842, 2023). "The findings contribute to the limited literature on PLEKHM2-associated cardiomyopathy." (PMID 40054934, 2025). "However, few studies have explored the deep molecular mechanisms of PLEKHM2 deficiency-mediated cardiomyopathy." (PMID 38490981, 2024). "Taken together, these results suggested that impaired mitochondrial clearance and increased ROS levels play important roles in PLEKHM2-deficient cardiomyopathy, and PLEKHM2-WT overexpression can improve mitochondrial function and rescue PLEKHM2-deficient cardiomyopathy." (PMID 38490981, 2024). "Importantly, our results suggested that impaired mitochondrial clearance with elevated ROS levels played an important role in the disease progression of PLEKHM2-deficient cardiomyopathy." (PMID 38490981, 2024). "Additionally, we showed that PLEKHM2-WT overexpression restored autophagic flux and ameliorated mitochondrial function, ultimately rescued PLEKHM2-deficient cardiomyopathy." (PMID 38490981, 2024). "Thus, it is necessary to further elucidate the underlying mechanism of PLEKHM2 in regulating autophagy, which aid in the treatment of PLEKHM2-deficient cardiomyopathy." (PMID 38490981, 2024). "To investigate whether oxidative stress accelerates the progression of PLEKHM2-deficient cardiomyopathy, we evaluated the effects of LPS administration on the calcium transient and myocardial contractility of WT hiPSC-CMs and PLEKHM2-KO hiPSC-CMs." (PMID 38490981, 2024). "However, we found that RAPA treatment cannot completely correct impaired autophagy caused by PLEKHM2 deficiency, but partially improves the disease phenotype of PLEKHM2-deficient cardiomyopathy." (PMID 38490981, 2024). "We next investigated whether PLEKHM2-WT overexpression could restore autophagic flux in PLEKHM2-KO hiPSC-CMs and rescued the disease phenotype of PLEKHM2-deficient cardiomyopathy." (PMID 38490981, 2024). "We reidentified all five loci harboring Mendelian cardiomyopathy-linked genes found in prior common variant analyses of DCM (ALPK3, BAG3, FLNC, PLEKHM2, and TTN)." (PMID 32382064, 2020). "Previous studies have reported the important role of PLEKHM2 in patient-derived fibroblasts or HeLa cells, but there is still a lack of suitable in vivo or in vitro cardiomyopathy models to reveal the effects of PLEKHM2 deficiency on cardiomyocytes or heart tissues." (PMID 38490981, 2024).
heart failure (3 papers, 2022 to 2025). Inability of the heart to pump blood at an adequate rate to meet tissue metabolic requirements. "•The patient's progression from heart failure to critical cardiogenic shock and the rare PLEKHM2 mutation underscore the complexity of advanced heart failure therapies, including extracorporeal membrane oxygenation, LVAD, and heart transplantation." (PMID 40054934, 2025). "Overall, these findings corroborate the strong link between PLEKHM2 deficiency and DCM, which manifests as reduced contractility and impaired calcium handling, along with sarcomeric disorganization and dysregulated expression of heart failure markers." (PMID 38490981, 2024). "Clinical neurodegeneration has not been reported in homozygous PLEKHM2[delAG] patients, though it might be as a result of the premature death of these patients due to heart failure." (PMID 36555735, 2022).
Salmonella Infections (2 papers, 2022 to 2023). Infections with bacteria of the genus SALMONELLA. "To test functionally the impact of RUFY3 on EL function, we performed Salmonella infection, since ARL8b/PLEKHM2/HOPS- and Rab7/PLEKHM1-dependent EL mobilizations are particularly important for the maturation of Salmonella-containing vacuoles (SCV) and bacterial replication in macrophages." (PMID 37463962, 2023).
autism spectrum disorder (1 paper, 2022). A spectrum of developmental disorders that includes autism, and Asperger syndrome. "The dysregulation in PLEKHM2[delAG] cultures activity is reminiscent of the neural behavior in epilepsy, autism spectrum disorder (ASD) or ALS/FTD." (PMID 36555735, 2022).
influenza (1 paper, 2025). An acute viral infection of the respiratory tract, occurring in isolated cases, in epidemics, or in pandemics; it is caused by serologically different strains of viruses (influenzaviruses) designated A, B, and C, has a 3-day incubation period, and usually lasts for 3 to 10 days. "This proteoform, generated by +1 PRF with a slippery site similar to the one identified in influenza, is necessary along with the PLEKHM2-CT proteoform to promote myocardial contraction." (PMID 41134891, 2025). "S2, A and B), indicating that similar to influenza, PLEKHM2 only requires its slippery site to induce +1 PRF." (PMID 41134891, 2025).
lung adenocarcinoma (1 paper, 2025). A carcinoma that arises from the lung and is characterized by the presence of malignant glandular epithelial cells. "Among the five cases, one case was detected in the component of SCLC combined with lung adenocarcinoma, and one case carrying PLEKHM2-ALK fusion mutation." (PMID 40136367, 2025).
small cell lung carcinoma (1 paper, 2025). Small cell lung cancer (SCLC) is a highly aggressive malignant neoplasm, accounting for 10-15% of lung cancer cases, characterized byrapid growth, and early metastasis. "PLEKHM2-ALK: a novel fusion in small-cell lung cancer and durable response to ALK inhibitors." (PMID 40136367, 2025).
Ventricular arrhythmia (1 paper, 2024). "This is consistent with the disease phenotype previously reported in cases of homozygous frameshift mutations in PLEKHM2, which were characterized by systolic dysfunction and ventricular arrhythmia." (PMID 38490981, 2024).
cardiovascular disease (1 paper, 2022). "PLEKHM2 was linked to autophagy regulation in the context of cardiovascular disease, however its role in the context of neurodegeneration remains largely unknown." (PMID 36555735, 2022).
infection (1 paper, 2024). The state of being infected such as from the introduction of a foreign agent such as serum, vaccine, antigenic substance or organism. "Day 3 after Ad-mRFP-EGFP-LC3 infection, we observed a significant accumulation of autophagosomes (GFP+/RFP+ puncta) with increasing starvation duration in both WT hiPSC-CMs and PLEKHM2-KO hiPSC-CMs." (PMID 38490981, 2024).
neurodegenerative disease (1 paper, 2022). A disorder of the central nervous system characterized by gradual and progressive loss of neural tissue and neurologic function. "DCM-LVNC patients died before any neurological disorder was detected; it is known that many neurodegenerative diseases are age related and therefore reduction in autophagic flux may have a cumulative effect, especially since PLEKHM2 transcripts are highly expressed in the brain." (PMID 36555735, 2022).
PLEKHM2 also shares sentences with these, for which no sentence is quoted: Arrhythmia (1 paper); atrial fibrillation (1); cancer (1); dilatation (1); epilepsy (1); insomnia (1); left ventricular noncompaction (1); long-QT syndrome (1); neurological disorder (1).